IL5 (interleukin 5)
Diseases named in the same sentence as IL5 in open-access papers (continued):
Sharing a sentence is not in itself a finding about the gene and the disease.
asthma (continued). "Our data underline a disconnect between clinical features and underlying inflammation, suggest IL-5 production is relatively steroid insensitive, and highlight the expression of YKL-40 in patients with neutrophilic inflammation and the expression of MMPs in patients with severe asthma." (PMID 26851968, 2016). "Our data demonstrated that reinfected mice showed an increased production of IL-17A, IL-6, TNF-α, IL-4 and IL-5, suggesting a pattern of mixed Th2/Th17 responsiveness, which was previously observed in studies with helminths and also allergic disorders, such as rhinitis and asthma." (PMID 26814713, 2016). "Airway inflammation is essential to the pathogenesis of asthma and is triggered by respiratory viral infections and inhaled allergen, leading to the activation of T helper 2 (Th2) cell differentiation and the secretion of Th2 cytokines such as IL-4, IL-5, and IL-13." (PMID 27274620, 2016). "Furthermore, based on the subgroups analysis, we could know that anti-interleukin 5 can significantly improve the FEV1 of severe asthma (MD = 0.11, P<0.001) and eosinophilic asthma (MD = 0.11, P = 0.001)." (PMID 27875559, 2016). "Similarly, IL-5 aids the production, maturation, and activation of eosinophils which contribute to airway inflammation and obstruction and are involved in longer-term asthma-related inflammatory processes." (PMID 27965775, 2016). "Further, we have shown that, although a variety of Th2 cytokines as well as IL-25 have been implicated in causing remodelling changes in human and murine airways in asthma, only IL-25, and not IL-4, IL-5 or IL-13 is able directly to induce angiogenesis by human vascular endothelial cells." (PMID 25889697, 2015). "Thus, we determined a significant increase in sputum IL-5 levels in the patients with allergic asthma, and it correlated with the migrated peripheral blood eosinophil count in allergen-induced late-phase airway inflammation in asthma patients." (PMID 25829869, 2015). "It has long been known that asthma is a disease linked to the activation of helper Th2-lymphocytes (whose key cytokines are mainly IL-2, IL-3, IL-4, IL-5, IL-9, IL-13 and GM-CSF) with a concomitant lack of inhibition by Treg lymphocytes for defective production of IL-10." (PMID 25671117, 2015). "Therefore, two different and nonmutually exclusive proinflammatory pathways activated by either allergen-specific Th2 lymphocytes or allergen-independent innate ILC2s, both leading to IL-5 production, are responsible for eosinophilic airway inflammation in asthma." (PMID 25878402, 2015). "Therefore we cannot exclude the possibility that the association between allergen-specific IL-5 responses and asthma and atopy is different in children without a family history of asthma." (PMID 24875149, 2014). "In addition, sub-sets of patients that are aspirin-sensitive/induced asthma or present with sinusitis might also benefit from anti-IL5 therapy." (PMID 25709744, 2014). "Another anti-IL5 mAb (IgG4/k) Reslizumab, showed similar reduction in sputum eosinophils, significant improvement in lung function (P= 0.002, vs. placebo) and a trend towards improved asthma scores (P= 0.054, vs. placebo) in patients diagnosed with severe refractory eosinophilic asthma." (PMID 25709744, 2014). "Furthermore, many other genes were related to asthma, such as IL-4, IL-5, and PAI-1." (PMID 23841068, 2013). "Moreover, an increase in the airway hyperresponsiveness of asthma and airway remodeling may be due to increased production of IL-4, IL-5, IL-6, and IL-13 in the inflammated airways." (PMID 23533467, 2013). "A recent study showed that the only biomarkers that could distinguish severe or moderate asthma from mild asthma are neutrophil count and IL-8, out of the eight potential biomarkers (IL-8, neutrophils, eosinophils, IL-1Rα, IL-1α, IL-5, IL-6, and RANTES) investigated in BALF." (PMID 23355837, 2013). "Furthermore, IL-5 is currently investigated as a cytokine based therapy in sepsis and asthma." (PMID 23472217, 2013).
asthma (continued). "As IL-5 is a key cytokine in eosinophil differentiation and maturation in the bone marrow as well as in recruitment and activation at sites of allergic inflammation, IL-5 inhibition may have a beneficial therapeutic effect in asthma by preventing eosinophilic inflammation in pulmonary tissue." (PMID 23544105, 2013). "Thus, IL-5 inhibition may have a beneficial therapeutic effect in asthma by preventing eosinophil maturation, function, or migration into pulmonary tissue." (PMID 23544105, 2013). "The suppression of all the symptoms of asthma in the present study was associated with reduced levels of various Th1 cytokines (TNF-α, IL-6, and IL-1β), with reduced levels of various Th2 cytokines (IL-4, IL-5 and IL13) and with reduced levels of a Th17 cytokines (IL-17F) in splenocytes." (PMID 23346203, 2012). "Moreover, it is well established that there is a strong interaction between eosinophils and Th2 cells in the asthmatic airways and that Th2 cell-derived cytokines, namely IL-4, IL-5, and IL-13, play critical roles in orchestrating and amplifying allergic inflammation in asthma." (PMID 21772663, 2011). "In addition, we found that genetic deficiency in IL-5, a central mediator of allergy and asthma, has no impact on urethane-induced adenocarcinoma formation." (PMID 20796309, 2010). "In an animal model of asthma intratracheally delivered AP-1 decoy oligodeoxynucleotides attenuate eosinophilic airway inflammation, airway hyperresponsiveness, mucous cell hyperplasia, production of allergen-specific immunoglobulins, and synthesis of IL-4, IL-5, and IL-13 in the lung." (PMID 18315837, 2008). "Using IL-5 deficient animals can not develop the asthma models." (PMID 16677400, 2006). "Therefore, the melioration of asthma clinical symptoms in CRS-asthma patients may be contributed by the reduction of IL-5 production, at least in part." (PMID 16677400, 2006). "This systematic review is the first comprehensive synthesis of evidence on predictors of response to anti‐IL5/5Rα, −4Rα, and anti‐TSLP therapies for severe asthma." (PMID 40956008, 2026). "This systematic review synthesised and evaluated the quality of evidence on predictors of response to anti‐IL5/5Rα, 4Rα, and anti‐TSLP for severe asthma." (PMID 40956008, 2026). "The main molecular pathways of asthma include T2 inflammation, mediated by Th2 and ILC2 cells, eosinophils, and the cytokines IL-4, IL-5, and IL-13, as well as non-T2 inflammation, mediated by neutrophils, macrophages, and the cytokines IL-1, IL-6, and IL-17." (PMID 40136501, 2025). "In vitro, knocking down Kif3a increased epithelial apoptosis, boosted CCL17, IL‐5, and IL‐8 transcription, and raised COX‐2 protein levels and β‐catenin translocation; Conversely, Kif3a overexpression greatly alleviates asthma." (PMID 39949885, 2025). "Moreover, Laura Bergantini and her colleagues demonstrated that therapeutic intervention with anti-IL-5 elicits a restorative equilibrium between regulatory T cells and effector T cells within the pulmonary microenvironment of individuals afflicted with severe asthma." (PMID 40303400, 2025). "Oral administration of L. reuteri ATCC 23272 also resulted in immunoregulatory effects, with elevated IL-10 levels and reduced levels of IL-5, IL-13, MCP-1, and TNF-α in OVA-induced asthma mice." (PMID 39820222, 2025). "Central to the eosinophilic inflammation seen in many asthma phenotypes are TH2 lymphocytes, which secrete IL-4, IL-5, and IL-13 in large amounts." (PMID 40732309, 2025). "Recently, monoclonal antibodies such as anti-interleukin-5 (Anti-IL-5) and anti-interleukin-5 receptor alpha (Anti-IL5R) have been used to control patients with severe asthma." (PMID 40804423, 2025). "Reslizumab is an interleukin-5 (IL-5) antagonist monoclonal antibody therapy, approved by the Food and Drug Administration (FDA) for adults with severe asthma with eosinophilic phenotype, which is a result of eosinophil proliferation." (PMID 41393680, 2025).
asthma (continued). "In the experiment, after OVA stimulation, the levels of IL-4, IL-5, IL-13, and TNF-α in BALF and the level of IgE in the serum of mice in the asthma model group were significantly elevated, indicating that Th2 cells were overly active." (PMID 40563981, 2025). "As described in the features section, each disease class was mapped to literature-supported protein and gene expression profiles (MMP-9 and TGF-β for bronchiectasis, CRP and IL-6 for pneumonia, and IL-5 and YKL-40 for asthma)." (PMID 40806268, 2025). "Similarly, asthma patients receiving conventional therapy alongside six months of oral choline supplementation exhibited significant reductions in circulating eosinophils and factors involved in bronchial hyperreactivity, such as IL-5 and cysteinyl leukotrienes (Cys-LT)." (PMID 40821837, 2025). "A systems pharmacology approach has identified the capacity of baicalin to target 48 asthma-related genes such as IFNγ, IL4, IL5, IL10, IL13, and TNFα and signaling pathways, reinforcing its polypharmacological properties." (PMID 40598285, 2025). "Reslizumab is a humanized IL-5 antagonist IgG4κ monoclonal antibody approved by the FDA and EMA as an add-on maintenance treatment for patients aged 18 years and older with severe asthma and an eosinophilic phenotype." (PMID 40149651, 2025). "In an OVA-induced asthma mouse model, TSG significantly modulated immune responses by suppressing Th2 cytokines, such as IL4 and IL5, and reducing total IgE and OVA-specific IgE levels, which are typically elevated in asthma." (PMID 40598285, 2025). "H2L5186303, an antagonist of LPA2, suppresses increases in eosinophil counts and Th2 cytokine (IL-5 and IL-13) in BALF in a murine model of asthma after allergen challenges." (PMID 40001485, 2025). "In asthma patients, including Th2 cell transcription factor, GATA3 the high levels of Th2-cell related cytokines such as IL-4, IL-5 and IL-13 were observed." (PMID 40323927, 2025). "Reslizumab and benralizumab are two additional anti-IL-5 antibodies that have recently received FDA approval for their safety and effectiveness in lowering asthma exacerbations." (PMID 40136649, 2025). "T2-high asthma, is the most recognized phenotype driven by type 2 helper (Th2) cells and innate lymphoid cells (ILC2), producing cytokines as IL-4, IL-5, and IL-13, These cytokines promote allergic inflammation and eosinophil recruitment." (PMID 41278227, 2025). "In a previous study, WEIF was revealed to reduce the serum levels of Th2 cytokines (IL-4, IL-5, and IL-13) and IgE in an OVA-induced asthma model by inhibiting the JAK/STAT signaling pathway." (PMID 40806199, 2025). "To evaluate this further, we investigated the direct effects of IL-5 on fibroblast activation and ECM remodelling, using primary airway fibroblasts cultured from endobronchial biopsies from patients with asthma." (PMID 41188935, 2025). "In asthma patients, eosinophils and CD4+ lymphocytes that secrete IL-5 are often detected in blood samples and fluid from lung lavage procedures." (PMID 40558541, 2025). "The relevance between the FEO‐03 network and asthma on the KEGG Pathways database presented EPX, IL4, IL5, IL13, CD40LG, TNF, and IL10 according to p value." (PMID 40777200, 2025). "In conclusion, both anti-IgE and anti-IL-5 treatments are highly effective in reducing exacerbations, symptom burden, and daily OCS requirements in severe asthma patients." (PMID 40047156, 2025). "This suggests that IL-5 may synergize with other cytokines such as IL-4 and IL-13 that are known to have a fibrotic by stimulating airway fibroblasts, further exacerbating airway remodelling, positioning it as a potential therapeutic target for fibrosis-related complications in asthma." (PMID 41188935, 2025). "In ovalbumin (OVA)-induced murine asthma, RvD1 reduced BALF eosinophils and lymphocytes, alleviated AHR, and lowered IL-5 and IL-23 levels while enhancing allergen phagocytosis by lung macrophages." (PMID 39720728, 2024).
asthma (continued). "IL5 and IL13 are major cytokines involved in asthma pathogenesis, related to differentiation, production, maturation, and activation of eosinophils, activation of fibroblasts, increased mucus production, and airway hyperresponsiveness." (PMID 38655128, 2024). "Here, administration of reticuline decreased the production of IL‐17A, MIP‐2, IL‐1β, IL‐5, and RANTES in lung tissues of mice with obesity‐related asthma induced by HDM or OVA." (PMID 38286741, 2024). "For instance, patients with both CRSwNP and asthma may benefit more from dupilumab as several studies have demonstrated its superior efficacy in managing both nasal and lower respiratory symptoms when compared to anti-IgE or anti-IL-5 therapies, which often show inadequate upper airway control." (PMID 39598027, 2024). "These predictors include eosinophilia, asthma, AERD, preoperative polyp severity, residual ethmoid cells, specific cytokine expressions (e.g., IL-5), prior ESS, and demographic factors such as age and sex." (PMID 39328679, 2024). "Overall, most physicians indicated preferring an anti-IgE for allergic asthma (59% of physicians), an anti-IL5 for eosinophilic asthma (87%), and an anti-TSLP for Type 2 Low asthma (68%)." (PMID 38637825, 2024). "For example, in type 2-high asthma, TH2 cells and ILC2s are significant IL-4, IL-5, and IL-13 sources; furthermore, infiltrating mast cells, eosinophils, and basophils play vital roles in producing type 2 cytokines." (PMID 39439788, 2024). "Our findings indicate that several cytokines, including IL-5, IL-17A, IL-22, IL-33, TNF-α, leptin, and IL-10 were independently influenced by asthma and obesity." (PMID 39902293, 2024). "ILC2s release type 2 cytokines (such as IL-5 and IL-13) and growth factors (such as AREG) in inflamed and injured lung tissues in patients with chronic obstructive pulmonary disease and asthma." (PMID 39405112, 2024). "Key molecular pathways of refractory asthma include T2 inflammation mediated by Th2 and ILC2 cells, eosinophils, and cytokines including IL-4, IL-5, and IL-13." (PMID 39194521, 2024). "In the ovalbumin-induced rat asthma model, FXR reduces airway inflammation by preventing inflammatory cell infiltration and inhibiting IL-4, IL-5, and IL-13 secretion, likely through antagonizing NFκB signaling and its target genes." (PMID 39411430, 2024). "The concentrations of cytokines such as IL-4, IL-5, IL-13, and TSLP in serum, sputum, and bronchoalveolar lavage fluid (BALF) in asthma have been reported to range from 1 to 100 pg/ml (approximately 0.7–70 pM)." (PMID 39624446, 2024). "It was also found that there is a link between increased levels of IL-5 in serum and BAL fluid and the increased severity of asthma." (PMID 39062104, 2024). "Our results have shown that the increased expression of CTSC also promoted the infiltration of inflammatory cells and the production of inflammatory factors (e.g., IL-5, IL-13, and IL-17A) in the HDM-induced asthma model and SA model." (PMID 39436705, 2024). "Preliminary research from our group in an asthma model induced with OVA in BALB/c mice showed that CO treatment regulates eosinophils, neutrophils, and the inflammatory markers IL-4, IL-5, IgE, IL-17, TNF-α, and IFN-γ." (PMID 38666018, 2024). "Increasing evidence indicates that biological therapies targeting IgE, IL-5/IL-5Rα, TSLP and IL-33/ST2 can improve not only clinical symptoms but also certain features of airway remodelling in asthma." (PMID 38609094, 2024). "Il-5-inhibiting monoclonal antibodies, such as mepolizumab, have been approved by the FDA for eosinophilic asthma, as an add-on treatment for severe asthma, and for adult patients with eosinophilic granulomatosis with polyangiitis." (PMID 39040614, 2024). "Most asthma biologics that are approved by the US Food and Drug Administration (FDA) target T2 inflammation with specific monoclonal antibodies to IgE, and the IL-5 and IL-4/IL-13 signaling pathways." (PMID 39194521, 2024).
asthma (continued). "The expression levels of ITGA4 and ITGB2 in IL‐5‐activated eosinophils and that of CCR3 in IL‐5‐ or IL‐17‐activated eosinophils were significantly higher for patients with asthma than for normal individuals." (PMID 39575691, 2024). "It is interesting that the level of IFN‐γ remained relatively stable compared with the varying levels of IL‐4, IL‐5, and IL‐13, despite a slight increase in the number of Th1 cells and level of IFN‐γ in the lungs during acute asthma exacerbation." (PMID 38938285, 2024). "Then, we assessed the levels of IgE, Th2 cytokines (IL-4, IL-5, and IL-13), eotaxin, TGF-β1, and MUC5AC using ELISA kits to detect the effect of scutellarin on the release of asthma-related cytokines in ovalbumin-challenged mice." (PMID 38168709, 2024). "Note that the frequency of IL5+ and IL13+ CD4 T cells was low in control wild type mice in our asthma model." (PMID 37575259, 2023). "The results of our study do not explain the differences in the response to the therapy with anti-IL5 biologicals between COPD and asthma patients, as the CD125 (IL-5 receptor) level was similar in both diseases." (PMID 37371101, 2023). "IL-5 and IL-13 secretion was analyzed by ELISA, and again, the two TH2 cytokines were elevated in asthma groups, but the amounts of secreted cytokines were similar in the asthma groups." (PMID 37443808, 2023). "Vitamin E and selenium have been shown to affect Th2 cytokines (IL-4, IL-5, and IL-13) as well as their upstream cytokines (IL-25 and IL-33), suggesting that they may be a beneficial treatment for the management of allergic diseases such as allergic rhinitis and asthma." (PMID 37513609, 2023). "They observed a reduction in the blood levels of IL-4, IL-5, IL-13, and monocyte chemoattractant protein-1 (MCP-1) and an improvement in bronchial hyperreactivity (BHR) and FEV1." (PMID 36873818, 2023). "In asthmatic airways, IL-5 recruits eosinophils and contributes to the induction of airway hyperreactivity (AHR), and the level of IL-5 correlates with asthma severity." (PMID 36851616, 2023). "In the present study, there was an increase in the inflammatory markers involved, such as IL-1β, IL-4, IL-5, IL-6, IL-10, IL-13, IL-17, IFN-γ, and TNF-α, in the experimental model of asthma-COPD overlap." (PMID 37511021, 2023). "Anti-IL5, anti-IL4R and anti-IgE mAbs have been used to improve outcomes from patients suffering from T2-high asthma endotypes." (PMID 37334374, 2023). "Sputum IL-5 was measured by the ELISA kit and the SERS biosensor, respectively, in clinical subjects with asthma." (PMID 38149176, 2023). "We also detected levels of oxidative stress markers (MDA, CAT and SOD), and frequent inflammation cytokines (IL-4, IL-5 and IFN-γ) in IL-13-induced BEAS-2B cells and BALF fluid of asthma mice." (PMID 36788676, 2023). "In CRS, as in asthma, the activation of ILC-2 cells leads to the release of cytokines (Il-9, Il-4, Il-5, and IL-13) stimulating a Th-2 inflammatory response." (PMID 37108417, 2023). "Increased secretion of Th2-type cytokines, such as IL-4, IL-5, and IL-13, in the allergic airway results in increased recruitment of inflammatory cells and airway hyperresponsiveness, suggesting that airway inflammation may be related to the severity of asthma." (PMID 36717898, 2023). "In CRS, as well as in asthma, the activation of ILC-2 cells leads to the release of cytokines (Il-9, Il-4, Il-5, and IL-13) that promote a Th-2 inflammatory response." (PMID 37947596, 2023). "Biologics targeting IgE, IL-4, IL-5, IL-13, and TSLP are used for uncontrolled severe asthma; their targets are all mediators produced by cells in the microenvironment of ILC2s." (PMID 36941691, 2023). "We found that the mRNA expression levels of several inflammatory factors, such as IL-4, IL-5 and TNF-α, were significantly lower in the PP121 group than in the asthma group." (PMID 37936054, 2023).